CHRM4 (cholinergic receptor muscarinic 4)
Diseases named in the same sentence as CHRM4 in open-access papers (continued):
Sharing a sentence is not in itself a finding about the gene and the disease.
myopia (3 papers, 2009 to 2024). "As with CHRM1, CHRM4 encodes a receptor important in the progression of myopia and also needs to be investigated." (PMID 19753311, 2009). "Much work over centuries has implicated cholinergic signaling and cholinergic receptors in myopia, including the M4 muscarinic receptor subtype which is the product of the ChRM4 gene in chick." (PMID 39028695, 2024). "Comparison between muscarinic receptor mutants showed that M1 (Chrm1), M4 (Chrm4) and M5 (Chrm5) mutants had significantly higher myopia in the lens-treated eyes than did M2 and M3 mutants." (PMID 23649821, 2013).
psychosis (3 papers, 2023 to 2025). "Among the 170 propsychotic target genes, 8 were a high-confidence psychosis risk gene (GRIN2A, DRD2, CYP2D6, CHRNB4, CHRM4, GABBR1, GRM3, CHRNA3)." (PMID 40701976, 2025).
Headache (2 papers, 2022 to 2024). Cephalgia, or pain sensed in various parts of the head, not confined to the area of distribution of any nerve. "In this cohort, there were only correlations of CHRM4-Ab with immune symptoms and of ADRB1- and CHRNA1-Ab correlated with headache." (PMID 36238301, 2022).
preeclampsia (2 papers, 2021 to 2022). Preeclampsia is a hypertensive disorder of pregnancy that is characterized by new-onset hypertension with proteinuria presenting after 20 weeks of gestation, and depending on mild or severe forms may initially present with severe headache, visual disturbances, and hyperreflexia. "The analysis of the final models points toward a relevance of AR, VDR, SLC6A2, NOS3 and CHRM4 as targets for preeclampsia." (PMID 33546161, 2021). "The most relevant targets for preeclampsia were: AR, VDR, SLC6A2, NOS3 and CHRM4, while ABCG2, ERBB2, CES1 and REN led to the most relevant off-targets." (PMID 33546161, 2021).
anemia (1 paper, 2023). A reduction in the number of red blood cells, the amount of hemoglobin, and/or the volume of packed red blood cells. "Pharmacological inhibition of CHRM4 by the antagonist, PD102807, was found to promote the burst-forming unit erythroid, a critical cell type for treating anemias." (PMID 37142586, 2023).
dementia (1 paper, 2024). Loss of intellectual abilities interfering with an individual's social and occupational functions. "P-M26 featured muscarinic cholinergic receptors CHRM1 and CHRM4, which have both demonstrated promise as synaptic targets for cognitive and behavioral symptoms in dementia." (PMID 39107789, 2024).
Dyskinesia (1 paper, 2023). A movement disorder which consists of effects including diminished voluntary movements and the presence of involuntary movements. "In addition, striatal and nigral CHRM4 signaling leads to multilevel inhibition of striato-nigral pathways which can result in an attenuation of dyskinesia, which links the CHRM4 to dopaminergic activity in the CNS." (PMID 36909280, 2023).
Obesity (1 paper, 2025). Accumulation of substantial excess body fat. "Targeting a specific population of neurons by using NPGL-Cre mice to generate M4-KO mice would help clarify which neurons contribute to aberrant obesity due to dysregulated gene expression caused by the deletion of Chrm4." (PMID 40179260, 2025). "In this study, we investigated the role of muscarinic acetylcholine receptor M4 (mAChR-M4) in the regulation of obesity in Chrm4-knockout (M4-KO) mice." (PMID 40179260, 2025). "In conclusion, we demonstrated that the deletion of Chrm4 throughout the whole body caused obesity with advancing age without any defects in energy homeostasis or hyperphagia in mice." (PMID 40179260, 2025). "In addition, Npgl overexpression in the ICR mouse strain causes obesity with no increase in food intake, similar to that caused by the deletion of Chrm4." (PMID 40179260, 2025).
cancer (2 papers, 2022 to 2023). A tumor composed of atypical neoplastic, often pleomorphic cells that invade other tissues. "Comparing muscarinic receptor subtype expression levels in adenocarcinoma vs. normal colon samples, we consistently observed reduced CHRM1, CHRM2, and CHRM4 and increased CHRM3 RNA levels (log2fc normal relative to cancer tissue)." (PMID 35370785, 2022).
tumor (2 papers, 2018 to 2024). "In summary, ADT‐induced CHRM4 overexpression and activation drives NEtD and immunosuppressive tumor environment through AKT/MYCN/IFNA17 axis, which confers targeting CHRM4 as a potential treatment for NEPC." (PMID 39372390, 2024). "Additionally, pharmacological inhibition of CHRM4 with certinib suppresses tumor growth and NEtD of NEPC." (PMID 39372390, 2024). "Some of these selected genes, such as CHRM4 and SLC17A4, involve in small molecule transport, tumour signal transduction and organism metabolism balance." (PMID 30514856, 2018).
CHRM4 also shares sentences with these, for which no sentence is quoted: depression (2 papers); mental disorder (2); adenocarcinoma (1); Anxiety (1); autism (1); cocaine use disorder (1); Cognitive impairment (1); colon cancer (1); COVID-19 (1); delirium (1); epilepsy (1); Huntington disease (1); infection (1); memory impairment (1); metabolic syndrome (1); migraine (1); Parkinson disease (1); prostate adenocarcinoma (1); prostate tumors (1); rheumatoid arthritis (1); substance abuse (1).